TNF (tumor necrosis factor)
Diseases named in the same sentence as TNF in open-access papers (continued):
Sharing a sentence is not in itself a finding about the gene and the disease.
tendinopathy (41 papers, 2012 to 2025). "As inflammation is an underlying mechanism of tendinopathy pathogenesis, mitochondrial transfer suppressed the levels of pro-inflammatory markers (IL-1β, IL-6, and TNF-α), revealing a promising therapeutic strategy against inflammatory." (PMID 37101277, 2023). "Considering the recessive co-dominance model (TNF-α -308GG + GA versus AA) the TNF-α -308AA genotype was significantly associated with tendinopathy cases, either considering all cases, patellar and Achilles tendinopathies." (PMID 33985554, 2021). "We used IL-1β and TNF-α, two hallmark cytokines of inflammation in tendons, which are associated with tendon injury and tendinopathy in vivo and in vitro, to induce disease-relevant inflammation." (PMID 34127759, 2021). "TNFα alone can also trigger the IL-6 expression in the tenocytes and also a higher expression of IL-6 has been associated with tendinopathy." (PMID 33803624, 2021). "The aim of this study was to investigate the association between the TNF-α polymorphisms and tendinopathy in athletes." (PMID 33985554, 2021). "Network-based assessment indicated that key targets associated with NGR1 in treating tendinopathy may potentially include IL-6, TNF, and MMP9." (PMID 40697661, 2025). "TNF-α TCA haplotype was associated with increased tendinopathies risk, either considering all cases (OR: 2.6, 95 % CI: 1.3–5.3), patellar (OR: 3.3, 95 % CI: 1.5–7.3), rotator cuff (OR: 3.1, 95 % CI: 1.4–7.2) or Achilles tendinopathies (OR: 3.8, 95 % CI: 1.1–12.7)." (PMID 33985554, 2021). "Our data partially support this hypothesis, given the negative relationships observed between AT CSA and pro-inflammatory cytokines TNF-α, IL-6 and IL-1β, all have been associated with the development of tendon disorders." (PMID 33484409, 2021). "Despite the different risk factors different types of tendinopathies, overloading and mechanical stress may induce the secretion of TNF-α by tenocytes and cause change cellular proliferation, onset of pain and ECM degradation." (PMID 33985554, 2021). "Thus, this study aimed to investigate the association between the TNF-α polymorphisms and tendinopathy in athletes." (PMID 33985554, 2021). "We hypothesized that the TNF-α SNPs could be associated with a risk of developing tendinopathy in athletes; since high TNF-α expression could be modulated by polymorphisms and TNF-α induce apoptosis and pro-inflammatory effects for primary degeneration of tendon." (PMID 33985554, 2021). "By intersecting the targets of NGR1 with those associated with tendinopathy, we constructed a PPI network, and the results showed that targets such as IL-6, TNF, AKT1, MMP9, and MMP3 are valuable in assessment." (PMID 40697661, 2025). "The KEGG analysis results suggested that the signaling pathways potentially involved in the treatment of tendinopathy with NGR1 include the TNF signaling pathway, NF-κB signaling pathway, and PI3K-Akt signaling pathway, among others." (PMID 40697661, 2025). "First, their anti-inflammatory effects are readily apparent in preclinical studies which have shown the downregulation of TNF-a in wound and OA models, decreases in MMPs in tendinopathy, and increased expression of M2 macrophages in adhesion models." (PMID 39062117, 2024). "Taken together, our findings suggest that diseased cells contribute to tendinopathy pathogenesis by activating the TNF signaling pathway." (PMID 37223090, 2023). "Of course, we have discussed the similarities and differences between supplementing TNF and IL-1β in tendinopathy inflammation for the reviewer's reading." (PMID 37600349, 2023). "Inflammatory mediators (IL-1β, IL-6 and TNF-α) have been reported to be highly expressed in tendon diseases and accelerate the progression of tendinopathy." (PMID 35458235, 2022). "Upregulation of inflammatory mediators (e.g., IL1β, IL1, IL6, and tumor necrosis factor-α) strongly suggests that inflammation is a key process in tendinopathy." (PMID 35689230, 2022).
tendinopathy (continued). "Tenocytes also have receptors for TNF-α, and in vitro stimulation of tenocytes by TNF-α can aggravate inflammation in tendinopathy." (PMID 35897746, 2022). "An inflammatory infiltrate with a high content of pro-inflammatory cytokines such as IL-6, TNF-α, and IL-17 has been identified in tendon biopsies during the initial phase of the tendinopathy process." (PMID 34575523, 2021). "The expression of IL-21R is affected in the first phase of tendinopathy as seen in culture after chemical challenge with TNF-α, and IL-1β." (PMID 34863223, 2021). "Within the Brazilian population the TNF-α-308AA genotype is rarer (approximately 0–2 %), and was only observed in the tendinopathy cases (~ 2 %)." (PMID 33985554, 2021). "Pro-inflammatory cytokines, such as tumor necrosis factor alpha (TNF-α), and growth factors have been implicated as a mechanism in early stages of tendinopathies." (PMID 33985554, 2021). "A systematic review of cytokines in tendon disease reported that the expression of IL-1β, IL-6, and TNF-α in animal tendon injury models tended to increase from the early phase of tendon healing." (PMID 34090401, 2021). "Even though various cytokines have been discussed in the research field of tendon inflammation, IL-1β, TNFα, IL-6, and IL-10 are considered in various studies as the key cytokines in tendon diseases, as reported in a systematic review." (PMID 33803624, 2021). "An experimental tendinopathy model produced by overuse shown that TNF-α mRNA was increased 11-fold in torn supraspinatus tendon compared to controls." (PMID 33985554, 2021). "A recent study in a repetitive-use tendinopathy model of rat flexor tendons, observed increased TNFα in younger rats." (PMID 34350166, 2021). "The present results indicate a positive association between TNF-α TCA haplotype and the risk of developing tendinopathy (2-4-fold), which is observed when analyzing only the patellar, rotator cuff or Achilles subgroups." (PMID 33985554, 2021). "Two hundred and seventy athletes (135 tendinopathy cases and 135 controls) were included and genotyped (TNF-α -1031T > C; -857 C > T; -308G > A) using TaqMan validated assays." (PMID 33985554, 2021). "Our study showed that TNF-α insults TDSCs and contributes to the development of tendinopathy via increasing the activation of MAPK and NF-κB pathways." (PMID 33195199, 2020). "Recent analysis of tendinopathy biopsies showed a distinct inflammatory infiltrate in the initial phase of tendinopathy with a high content of pro-inflammatory factors such as IL-6, TNF-α and IL-17." (PMID 32443833, 2020). "Cytokines, such as interleukins, TNF-α, and interferon gamma are known to be key players in tendon disorders." (PMID 32075290, 2020). "As TNF-α was different between the tendinopathy and control group, correlations with potential confounding factors (physical activity, BMI, pain symptom duration) were determined to further explore this finding." (PMID 26925234, 2016). "Very little is known regarding the role of TNF-α signalling in tendinopathy, necessitating a broader view across other research fields." (PMID 26925234, 2016). "The finding for TNF-α was an unexpected finding as previous research mainly points toward an increased activation of the TNF-α system in tendinopathy and tendon overuse." (PMID 26925234, 2016). "As macrophages are the primary source of IL-1β and TNFα and this cell type has been identified in various tendinopathy and tendon healing models, we developed a more biologically relevant co-culture in vitro model for the current study." (PMID 25889287, 2015). "In fact, various inflammatory mediators like TNF-alpha, IL-6, IL-15, IL-18 have been shown to play a role especially in wound healing after injury and in early stages of tendinopathy." (PMID 22480275, 2012). "Moreover, TNF-α RNA (TNFA) was expressed at low abundance in early-stage tendinopathy; however, statistically significant differential expression was not apparent." (PMID 39988349, 2025).
tendinopathy (continued). "The IL-17A-induced expression of downstream inflammatory effectors IL-6, CXCL1 and MMP3 was completely inhibited by secukinumab, suggesting that IL-17A alone and in concert with TNF-α may promote inflammation in tendinopathy." (PMID 39988349, 2025). "IL-1β, IL-17, and TNF-α may contribute to tendinopathy by impairing the biological activity of tenocytes." (PMID 39850191, 2024). "This study showed that intact exogenous mitochondrial transplantation could have protective effects against TNF-α-induced damage in tenocytes and a collagenase-induced animal model of tendinopathy." (PMID 33925007, 2021). "As far as we know, there are no studies evaluating the influence of TNF-α SNPs as possible risk factors involved in the inflammatory molecular mechanism leading to tendinopathy." (PMID 33985554, 2021). "Moreover, the TNF-α -308AA genotype was only present in the tendinopathy cases, either considering all cases, patellar, rotator cuff or Achilles tendinopathies." (PMID 33985554, 2021). "In addition, TNF-α and its receptors were expressed in peritendinous tissue, and in rounded/enlarged nucleus human tenocytes, a typical characteristic of tendinopathy." (PMID 33985554, 2021). "This may explain the increased level of TNF-α mRNA found in the degenerate tendon; and consequently, contribute to inter-individual variation in tendinopathy development." (PMID 33985554, 2021). "Despite of the TNF-α -308AA genotype suggests a more likely of having tendinopathy nis more than one tendon, when to compared only tendinopathy cases group (one versus 2 or more affected tendons) there was not statistical power due to the decrease of the sample size (data not shown)." (PMID 33985554, 2021). "Tumor necrosis factor-α (TNF-α) plays an important role in initiating tendinopathy." (PMID 33195199, 2020). "Other potentially interesting biomarkers for musculoskeletal diseases, such as tendinopathy, include TNF-α, interleukin 1 beta (IL-1β), basic fibroblast growth factor (bFGF), interferon gamma (IFN-γ), platelet derived growth factor BB (PDGF-BB) and vascular endothelial growth factor (VEGF)." (PMID 26925234, 2016). "Together these data indicate that although the TNF-α system appears to be involved in tendinopathy, whether it is up or down regulated appears to depend on several factors." (PMID 26925234, 2016). "Therefore, it remains of interest to examine TNF-α levels, as well as other cytokines, in the very early stages of tendinopathy, which will be the focus of future research endeavours." (PMID 26925234, 2016). "qPCR analysis indicated elevated mRNA levels of TNF-α, IL-6, and MMP3 in the tendinopathy group, indicating the presence of inflammation in tendinopathic tissues." (PMID 39442875, 2025). "Tectorigenin, derived from Belamcanda chinensis, has been reported to prevent tendinopathy by inhibiting the MAPK and NF-κB pathways in TNF-α-treated TSCs." (PMID 39500862, 2024). "High levels of the tumor necrosis factor alpha (TNF-α) induce apoptosis and pro-inflammatory effects for primary degeneration of tendon and development of tendinopathy." (PMID 33985554, 2021). "Another study showed that TNF-α can induce TDSC inflammation and apoptosis, and promote the development of tendinopathy by up-regulating the activation of MAPK and NF-κB pathways." (PMID 34714891, 2021). "The inhibition of TNF-α and targeting of MAPK and NF-κB offers potential in the treatment of tendinopathy." (PMID 33195199, 2020). "This included finding lower levels of TNF-α (and a lower level in PDGF-BB and a trend for a decrease in IL-1β) in the female tendinopathy group, as compared to the control female group." (PMID 26925234, 2016). "When separated by gender, serum TNF-α and PDGF-BB levels were lower in women with tendinopathy compared to women in the control group." (PMID 26925234, 2016). "Second, we focused on the central role of NF-kB in inflammation and in tendinopathy, which is activated by TNF rather than IL-1β." (PMID 37600349, 2023).
tendinopathy (continued). "Athletes with TNF-α TCA haplotype could be early subjected to cryotherapy after training and competition to avoid tendinopathy development." (PMID 33985554, 2021). "TNF-α concentration was lower in the entire tendinopathy group compared with the entire control group; none of the other cytokines were significantly different." (PMID 26925234, 2016). "This study identified lower serum TNF-α as a potential tendinopathy biomarker among females but not males." (PMID 26925234, 2016). "A strong correlation between physical activity level and serum TNF-α was seen in the male control group but not the male tendinopathy group, nor in any of the female groups." (PMID 26925234, 2016). "After excluding data with CV >15 % there was a clear trend towards significance for a difference in TNF-α levels between women with and without tendinopathy (p = 0.053)." (PMID 26925234, 2016). "Pro-inflammatory markers TNF-α and CD45 were upregulated in disease cells versus controls; therefore the findings of the present study support the concept that inflammation contributes to the pain symptomatology in tendinopathy." (PMID 26160609, 2015). "While some studies show TNFα in samples of human tendinopathy, others do not." (PMID 34350166, 2021). "First, TNF-α levels were lower in women with tendinopathy than women without tendinopathy." (PMID 26925234, 2016). "Notwithstanding this limitation, avoidance of painful activities might explain why there was the difference in TNF-α level between females with and without tendinopathy." (PMID 26925234, 2016). "A significant correlation was seen between TNF-α and physical activity level for all men, however, when examined by subgroup there was a correlation for the men of the control group but not those of the tendinopathy group." (PMID 26925234, 2016). "Furthermore, the molecular docking results presented the stable and high-affinity binding of NGR1 to TNF-α, IL-6, MMP3, MMP9, and MMP13, indicating that NGR1 may exert its therapeutic effects on tendinopathy by modulating inflammatory responses and cellular and extracellular matrix metabolism." (PMID 40697661, 2025). "However, in combination with TNF-α, all three IL-17 cytokines induce similar levels of IL6 and MMP3 mRNA expression, which could make not only IL-17A, but also IL-17F and IL-17AF interesting treatment targets in tendinopathy." (PMID 35004653, 2021). "Physical activity was correlated with TNF-α, PDGF-BB and IL-1β to varying extents for control subgroups, but not for the female tendinopathy group." (PMID 26925234, 2016). "Analysed by gender, TNF-α and PDGF-BB concentrations were lower in the female tendinopathy group but not the male tendinopathy group." (PMID 26925234, 2016). "Interestingly, proinflammatory and catabolic cytokines such as interleukin-1 beta (IL-1β), tumor necrosis factor alpha (TNF-α), and interferon gamma (IFN-γ) have been immunolocalized in horses with tendinopathy but not in healthy horses." (PMID 40284884, 2025). "However, the production of TNFα and CXCL10 chemokine and transient PMN cell infiltration in tendinopathies is independent of ASC inflammasomes." (PMID 39468985, 2024). "In vitro, stimulation of tenocytes with TNFα results in increased expression of adhesion proteins and inflammatory cytokines (IL6, IL8), that may add to the inflammatory milieu in tendinopathy, independent of immune cells." (PMID 34350166, 2021). "Finally, correlations between TNF-α and IL-1β, and between TNF-α and PDGF-BB were seen for all women but not when control and tendinopathy groups were examined separately." (PMID 26925234, 2016).
viral myocarditis (41 papers, 2013 to 2026). Myocarditis that is caused by an infection with a viral agent. "Tumor necrosis factor-α (TNF-α) is one of many cytokines released in this process and has been implicated as a driving factor for greater myocyte necrosis in the mouse model of viral myocarditis." (PMID 38785743, 2024). "We subsequently conducted a meta-analysis on the efficacy of serum TNF-α expression level and its diagnostic accuracy on acute viral myocarditis detection." (PMID 35602592, 2022). "In a coxsackievirus B3 (CVB3) murine myocarditis model, nicotine activated α7nAChR, increased STAT3 phosphorylation, reduced the expression of TNF-α and IL-6, and attenuated the damage due to viral myocarditis." (PMID 39206262, 2024). "miR-155 is also up-regulated in viral myocarditis; where it is expressed by infiltrating immune cells, and seems to be involved in TNF-α, IFN-γ and IL-6 production, as well as immune cell infiltration." (PMID 36072583, 2022). "A previous report showed that the levels of inflammatory cytokines, including TNF, are elevated in patients with viral myocarditis." (PMID 35163412, 2022). "Th1 cells and their proinflammatory cytokines, such as IL-1β and TNF-α, were shown to be etiological factors in the induction of viral myocarditis." (PMID 34452454, 2021). "KEGG pathway analysis showed that the proteins significantly changed in M1 macrophages were mainly involved in the pathways of transcriptional misregulation in cancer, NF-kappa B signaling pathway, TNF signaling pathway, and viral myocarditis." (PMID 34267761, 2021). "In contrast, overexpression of IL-6 significantly increases the expression of tumor necrosis factor α (TNF-α) and aggravates myocardial injury in viral myocarditis mice." (PMID 33099539, 2020). "TNF-α is involved in the pathogenesis of viral myocarditis, and TNF-α antibody treatment can significantly reduce the degree of myocardial damage and mortality." (PMID 33817135, 2019). "The purpose of this study was to investigate the diagnostic performance of serum CK-MB, TNF-α and hs-CRP in children with viral myocarditis (VMC)." (PMID 33817135, 2019). "The downregulated DEGs were enriched in pathways such as those of influenza A, viral myocarditis, and TNF signaling and GO terms such as cytoplasm, cell surface, and interferon gamma-mediated signaling pathway." (PMID 29686831, 2018). "We also conclude that blocking α7nAchR reduces the phosphorylation of STAT3, increases the expression of TNF-α and IL-6, aggravating viral myocarditis." (PMID 25396421, 2014). "Because nicotine is a α7nAchR agonist and methyllycaconitine is a α7nAchR antagonist, we conclude that α7nAchR activation increases the phosphorylation of STAT3, reduces the expression of TNF-α and IL-6, and, ultimately, alleviates viral myocarditis." (PMID 25396421, 2014). "In agreement with previous studies from our and other laboratories, we found that carvedilol improved the survival of mice and reduced myocardial inflammation and necrosis in murine viral myocarditis by downregulating the production of IL-6 and TNF-α." (PMID 24225056, 2013). "The expression and phosphorylation of CREB were decreased with concomitant increase of IL-6 and TNF-α in murine coxsackievirus-induced acute viral myocarditis." (PMID 24225056, 2013). "Carvedilol increased the cardiac CREB expression and phosphorylation and decreased the plasma catecholamine levels and the production of IL-6 and TNF-α with amelioration of acute viral myocarditis." (PMID 24225056, 2013). "Second, carvedilol increased cardiac CREB expression and phosphorylation and decreased the plasma catecholamine levels and the production of IL-6 and TNF-α with amelioration of acute viral myocarditis." (PMID 24225056, 2013).